RP1L1 (RP1 like 1)
Description:
Required for the differentiation of photoreceptor cells. Plays a role in the organization of outer segment of rod and cone photoreceptors (By similarity).
Synonyms: DCDC4B; OCMD; RP88
Tractability: No criterion of Open Targets' tractability assessment is met for any kind of drug.
Gene: Protein-coding gene on chromosome 8 (10,606,349 to 10,712,187, reverse strand). Ensembl gene ENSG00000183638.
Subcellular location: Cytoplasm, cytoskeleton, cilium axoneme; Cell projection, cilium, photoreceptor outer segment
Gene Ontology:
Biological process: photoreceptor cell maintenance; axoneme assembly; photoreceptor cell development; photoreceptor cell outer segment organization; retina development in camera-type eye; intracellular signal transduction
Cellular component: axoneme; photoreceptor connecting cilium; photoreceptor outer segment
Genetic constraint (gnomAD): Loss-of-function variants: 27 observed, 16.59 expected, observed/expected ratio (o/e) 1.63, 90% interval 1.18 to 1.94. The synonymous counts are far from expectation, so gnomAD's model fits this gene poorly and the ratio says little. Missense variants: 4,798 observed, 3,129.7 expected, observed/expected ratio (o/e) 1.53, 90% interval 1.5 to 1.57. Synonymous variants: 1,813 observed, 1,303.9 expected, observed/expected ratio (o/e) 1.39, 90% interval 1.34 to 1.45.
Gene-disease validity (ClinGen):
ClinGen rates the evidence that RP1L1 causes each of these diseases.
occult macular dystrophy (autosomal dominant): Definitive.
Homologues: Orthologues: chimpanzee RP1L1 (84% identical), macaque RP1L1 (54% identical), dog RP1L1 (43% identical), mouse Rp1l1 (37% identical), rat Rp1l1 (37% identical), zebrafish rp1l1a (17% identical), zebrafish rp1l1b (16% identical), tropical clawed frog rp1l1 (14% identical), Caenorhabditis elegans F27C1.11 (6% identical), Caenorhabditis elegans F27C1.13 (2% identical). Paralogues in human: RP1 (12% identical).
Diseases named in the same sentence as RP1L1 in open-access papers:
RP1L1 is named in the same sentence as 47 diseases in open-access papers, as found by Europe PMC text mining. Sharing a sentence is not in itself a finding about the gene and the disease. The quoted sentences say what the papers report.
occult macular dystrophy (23 papers, 2012 to 2025). "We identified the RP1L1 c.133C>T (R45W) mutation as the primary pathogenic variant in occult macular dystrophy (OMD)." (PMID 40450528, 2025). "RP1 like 1 is a retinal-specific protein, harmful variations in which cause occult macular dystrophy (OMD)." (PMID 40076632, 2025). "PKD1L2 is associated with polycystic kidney disease, and RP1L1 variants are associated with several retinal diseases including occult macular dystrophy." (PMID 35653351, 2022). "Pathogenic mutations in RP1L1 lead to photoreceptor degenerations such as occult macular dystrophy and retinitis pigmentosa." (PMID 33007938, 2020). "RP1L1 is associated with a spectrum of inherited retinal diseases including retinitis pigmentosa and occult macular dystrophy." (PMID 27439461, 2016). "Detailed genotype-phenotype analysis, such as the relationship between RP1L1 variants and occult macular dystrophy, demonstrates that genes with apparent dominant inheritance often have a complex relationship with disease." (PMID 23687434, 2013). "RP1L1 encodes for a protein that is part of the photoreceptor axoneme, and RP1L1 variants are associated with a spectrum of inherited retinal diseases including retinitis pigmentosa and occult macular dystrophy." (PMID 40110489, 2025). "In case rq2 with AD macular dystrophy caused by RP1L1, patients presenting with clinical symptoms of occult macular dystrophy (OCMD) caused by mutations in the RP1L1 gene belong to the subgroup of occult macular dysfunction syndromes, also known as Miyake disease." (PMID 38785568, 2024). "Potential phenocopies of the optical gap appearance on OCT imaging include achromatopsia (associated with CNGA3 or CNGB3 mutations), cone dystrophy (associated with GUCY2D or other genes), RP1L1-associated occult macular dystrophy, and acquired diseases such as solar retinopathy." (PMID 38066771, 2023). "RP1L1 was already a candidate for adRP but was previously associated with occult macular dystrophy." (PMID 22277662, 2012). "We retrospectively studied patients with RP1L1-associated occult macular dystrophy (OMD), Stargardt disease (STGD), and RP." (PMID 40208579, 2025). "Occult Macular Dystrophy (OMD) is a rare autosomal dominant disorder caused by pathogenic variants in the RP1L1 gene, which is crucial for photoreceptor function." (PMID 40364109, 2025). "Defects in RP1L1 cause occult macular dystrophy (OCMD, MIM 613587), an autosomal dominant macular dystrophy." (PMID 33748110, 2021). "Occult macular dystrophy (OMD), most commonly caused by mutations in the RP1L1 gene, presents with progressive central vision loss despite a near-normal fundus appearance." (PMID 40941642, 2025). "OCT alterations seen in PORT could resemble some macular diseases, such as RP1L1-pathogenic-variant-related occult macular dystrophy (OMD)." (PMID 40215251, 2025). "Finally, mutations in the retinitis pigmentosa-1-like-1 (RP1L1) gene are known to be causal for autosomal dominant occult macular dystrophy (OCMD)." (PMID 35982790, 2022). "This is reasonable when we correlate the clinical phenotypes; CEP290 is related to LCA, RP1L1 is related to occult macular dystrophy (OMD), ABCA4 is related to Stargardt disease and severe forms of autosomal recessive RP, and CYP4V2 is related to BCD." (PMID 33608557, 2021). "It is possible to speculate that the RP1L1 S564C mutation might somehow have an effect on the clinical phenotype in these MCD patients due to RP1L1’s association with two retinal disorders, occult macular dystrophy and retinitis pigmentosa." (PMID 27439461, 2016).
retinitis pigmentosa (11 papers, 2016 to 2025). Retinitis pigmentosa (RP) is an inherited retinal dystrophy leading to progressive loss of the photoreceptors and retinal pigment epithelium and resulting in blindness usually after several decades. "The purpose of our study was to illustrate a data-driven deep learning approach to predict the causative genes of IRD in macular dystrophy caused by ABCA4 and RP1L1 in comparison with retinitis pigmentosa caused by EYS gene aberration and normal subjects." (PMID 31093368, 2019). "Beispiele hierfür sind die autosomal-dominante okkulte Makuladystrophie (RP1L1-Gen) und die X‐chromosomale Retinitis pigmentosa (RPGR-Gen) – Letztere auch bei heterozygoten, weiblichen Merkmalsträgerinnen (Konduktorinnen)." (PMID 32458067, 2021). "RP1L1 mutations have been reported in cone and rod disease, including OMD, RP1L1 maculopathies, rod-cone dystrophy, and the rod degenerative disease retinitis pigmentosa (RP)." (PMID 33007938, 2020). "RP1L1 mutations have been reported to cause a diversity of human photoreceptor diseases that can affect cones and rods, while RP1 mutations have primarily been reported in retinitis pigmentosa cases, although there have been some cone diseases associated with RP1." (PMID 33007938, 2020).
retinal diseases (10 papers, 2015 to 2025). "In this category, other interesting results are represented by the discovery of two different subjects carrying biallelic LoF variants in the GRK1 and RP1L1 genes, both involved in retinal diseases." (PMID 33727708, 2021). "In the three affected members, we confirmed the known mutation, p.R45W in the RP1L1 gene and excluded the potential of additional pathogenic variants in other retinal disease related genes." (PMID 28838317, 2017). "To search for the possibility that the cone dystrophy phenotype of the patient was caused by a gene defect other than the RP1L1 mutation, we performed NGS analysis with an exon sequencing array targeting 123 known genes associated with retinal diseases." (PMID 25692141, 2015). "We searched the electronic patient records of our large inherited retinal disease cohort, quantifying numbers of males and females with the more common (non-ABCA4) inherited macular dystrophies (associated with BEST1, EFEMP1, PROM1, PRPH2, RP1L1, and TIMP3)." (PMID 38700873, 2024).
Macular dystrophy (5 papers, 2019 to 2024). Macular dystrophy is a nonspecific term for retinal degeneration, generally confined to the macula, usually presumed of genetic origin. "The de novo heterozygous c.3971A>G/p.Glu1324Gly of the RP1L1 was identified in a patient diagnosed with macular dystrophy (Case rq2)." (PMID 38785568, 2024). "Retinitis pigmentosa 1-like 1 gene (RP1L1, OMIM 608581) is the only confirmed associated gene and dominant mutations in RP1L1 are responsible for occult macular dystrophy." (PMID 34373789, 2021).
Retinal dystrophy (4 papers, 2016 to 2025). Retinal dystrophy is an abnormality of the retina associated with a hereditary process. "Of these patients, seven had monoallelic pathogenic variants in ABCA4, one had biallelic variants of uncertain significance (VUS) in ABCA4, two had monoallelic VUS in ABCA4, and eight harbored VUS in other retinal dystrophy-related genes, including KCNV2, RIMS1, CRB1, CFH, RP1L1, UNC119, and SEMA4A." (PMID 41234456, 2025).
cone dystrophy (3 papers, 2015 to 2023). An inherited ocular disorder characterized by the loss of cone cells, the photoreceptors responsible for both central and color vision. "The manifestations of RP1L1 pathogenic variants are complex and include both limited and diffuse forms of cone dystrophy." (PMID 30116628, 2018). "The RP1L1 mutation was the only one that cosegregated with the cone dystrophy phenotype in the homozygous state and both simulation programs predicted it to be damaging." (PMID 25692141, 2015). "In conclusion, our findings show the possibility that homozygous p.S1210P exchange in the RP1L1 gene can cause cone dystrophy, which would then extend the phenotype of OMD." (PMID 25692141, 2015). "Our findings indicate that a homozygous p.S1210P exchange in the RP1L1 gene can cause cone dystrophy." (PMID 25692141, 2015). "The purpose of this study was to determine whether an autosomal recessive cone dystrophy was caused by a homozygous RP1L1 mutation." (PMID 25692141, 2015). "We performed NGS analysis to search for possible candidate genes other than the RP1L1 that might have caused the cone dystrophy phenotype of patients." (PMID 25692141, 2015). "The purpose of this study was to determine whether autosomal recessive cone dystrophy was caused by homozygous RP1L1 mutations." (PMID 25692141, 2015). "We speculate that RP1L1 may modulate the effects of another cone dystrophy gene or autoimmune retinopathy contributing to allow sparing of the foveolar cones in the PCD phenotype." (PMID 30116628, 2018). "Genetic and phenotypic studies of the family members suggested that the homozygous p.S1210P mutation in RP1L1 is able to cause cone dystrophy without affecting heterozygous individuals." (PMID 25692141, 2015).
age-related macular degeneration (2 papers, 2020 to 2022). Age-related loss of vision in the central portion of the retina (macula), secondary to retinal degeneration. "Mutation of rp1l1 was found to result in progressive photoreceptor dysfunction and age-related macular degeneration-like pathology in zebrafish." (PMID 35563172, 2022). "Our mutant is a novel model of RP1L1-associated photoreceptor disease and the first zebrafish model of photoreceptor degeneration with reported subretinal drusenoid deposits, a feature of age-related macular degeneration." (PMID 33007938, 2020).
gastric cancer (2 papers, 2015 to 2024). A primary or metastatic malignant neoplasm involving the stomach. "Limited studies have reported RP1L1 mutations in gastric cancer." (PMID 38243319, 2024).
retinal degeneration (2 papers, 2016 to 2024). Degeneration of the retina. "The lipid abnormalities observed in the RPE of Elovl4b KO zebrafish are consistent with research on retinal degenerations in humans and Rp1l1 mutant zebrafish." (PMID 38342437, 2024).
autosomal recessive retinitis pigmentosa (1 paper, 2023). Autosomal recessive retinitis pigmentosa (RP) is an autosomally recessive inherited retinal dystrophy leading to progressive loss of the photoreceptors and retinal pigment epithelium and resulting in blindness usually after several decades. "OMD is associated with the mutations in the RP1L1 (retinitis pigmentosa 1-like 1) gene in an autosomal dominant fashion, while the same gene is also associated with autosomal recessive retinitis pigmentosa." (PMID 36835965, 2023).
Barrett esophagus (1 paper, 2024). Esophageal lesion lined with columnar metaplastic epithelium which is flat or villiform. "Additionally, one study showed a relationship between RP1L1 mutations and dopamine-agonist resistance in prolactinoma, and one meta-analysis identified that PRSS55-RP1L1 was probably associated with the risk of Barrett’s esophagus/esophageal adenocarcinoma in a sex dependent manner." (PMID 38243319, 2024).
breast invasive carcinoma (1 paper, 2024). "MUC4, RP1L1 and QRICH2 mutations were identified in at least three tumors, and these mutation also existed in breast invasive carcinoma databases (TCGA, Cell 2015; TCGA, Nature 2012)." (PMID 38243319, 2024).
colorectal cancer (1 paper, 2016). A primary or metastatic malignant neoplasm that affects the colon or rectum. "For RP1L1, recent results might offer a link between mutations in this gene and the development of gastric and colorectal cancers." (PMID 27150584, 2016).
cystic teratomas of the ovary (1 paper, 2022). "Among the 15 prevalent mutated genes, 8 with different variants in exons with changes in protein coding are important for the development of mature cystic teratomas of the ovary: FLG, MUC17, MUC5B, RP1L1, NBPF1, SLC29A3, SGK223, and FAM186A." (PMID 36289533, 2022).
inherited macular dystrophy (1 paper, 2023). "Recently, patients with inherited macular dystrophy and normal fundus caused by genes other than RP1L1 have been reported (hereditary non-RP1L1 OMD)." (PMID 37895218, 2023).
myopia (1 paper, 2024). "This RP1L1 variant was previously reported in a patient with RP sine pigmento masquerading as moderate myopia." (PMID 38785568, 2024).
retinopathy (6 papers, 2016 to 2024). "Several candidate genes associated with CQ/HCQ retinopathy were found, including RP1L1, RPGR and RPE65, with a difference of affected percentage over 50% in mutation between the case and control groups." (PMID 38548946, 2024). "Several candidate genes associated with CQ/HCQ retinopathy were found with exome sequencing, including RP1L1, RPGR, RPE65, CACNA2D4, EYS, RP1, IMPG1 and ABCA4." (PMID 38548946, 2024). "In this study, several candidate susceptibility genes including RP1L1, RPGR, RPE65 and CCDC66 were identified to be associated with CQ/HCQ retinopathy via exome sequencing and genome-wide association study." (PMID 38548946, 2024). "Several candidate susceptibility genes including RP1L1, RPGR, RPE65 and CCDC66 were identified to be associated with CQ/HCQ retinopathy." (PMID 38548946, 2024). "Seventy-five subjects with IRD or no ocular diseases have been ascertained from the database of Japan Eye Genetics Consortium; 10 ABCA4 retinopathy, 20 RP1L1 retinopathy, 28 EYS retinopathy, and 17 normal patients/subjects." (PMID 31093368, 2019). "Also, RP1L1, PROM1, CRX, CFI and CFB, and KCNJ13 have been linked to retinopathy." (PMID 33330132, 2020).
cancer (5 papers, 2015 to 2024). A tumor composed of atypical neoplastic, often pleomorphic cells that invade other tissues. "The associations between RP1L1 and cancer are basically unknown." (PMID 38243319, 2024). "Other cancer genes frequently altered in LC according to cBioPortal (e.g., ZFHX4, RYR2, CSMD3, FAT3, and RP1L1) were also found mutated at a high frequency in our cohort." (PMID 30925779, 2019). "Among them, the somatic mutation of RP1L1 and PRB1 caused gene activation with elevated mRNA expression in primary cancer, PM cancer or in both." (PMID 26330360, 2015). "Levels of proteins Rngtt, Rp1l1, Tacstd2, Zfyve26, and Zfyve27, which are known to promote a proliferative phenotype in various cancers, were decreased in the brain vasculature of TGF mice, likely as an attempt to attenuate vascular proliferation and remodeling." (PMID 38132326, 2023).
tumor (3 papers, 2015 to 2023). "Four somatic variations (RP1L1, PRB1, HS6ST3 and DCTN1) were simultaneously occurred in both primary tumor and PM cancer." (PMID 26330360, 2015).
RP1L1 also shares sentences with these, for which no sentence is quoted: Stargardt disease (4 papers); achromatopsia (2); Rod-cone dystrophy (2); autism (1); autoimmune retinopathy (1); autosomal dominant retinitis pigmentosa (1); chronic gastritis (1); Ciliopathies (1); congenital stationary night blindness (1); glioblastoma (1); Insulin resistance (1); lactic acidosis (1); Leber congenital amaurosis (1); macular degeneration (1); metastatic cancer (1); metastatic tumors (1); microphthalmos (1); nasopharyngeal carcinoma (1); neurodevelopmental disorder (1); Obesity (1); polycystic kidney disease (1); retinitis pigmentosa 1 (1); Roifman syndrome (1); Stickler syndrome (1); type 1 diabetes mellitus (1); type 2 diabetes mellitus (1); type II diabetes (1); uveitis (1).